TERT (telomerase reverse transcriptase)
Diseases named in the same sentence as TERT in open-access papers (continued):
Sharing a sentence is not in itself a finding about the gene and the disease.
bladder cancer (continued). "Our study mainly focused on the role of TERT mutation in bladder cancer stem cell regulation and tumorigenesis." (PMID 26143634, 2015). "TERT promoter mutations are identified in many malignancies including bladder cancer (BC) and upper tract urothelial carcinoma (UTUC)." (PMID 24742867, 2014). "Up to 84% of bladder cancer (BC) carry TERT promoter mutations and the mutant sequence is detectable in voided urine from mutation-positive BC patients." (PMID 25474136, 2014). "For instance, up to 80% of patients with bladder cancer (BC) carry TERT promoter mutations in their tumors, and detection of these mutations in urine has recently been tested at both diagnostic work-up and monitoring of recurrence." (PMID 24742867, 2014). "TERT promoter mutations in the urine of bladder cancer patients could be detected by droplet digital PCR in recent years." (PMID 40748011, 2025). "TERT promoter mutations were consistently found in more than one tumor sample from the same patient in 22 of the 29 cases, suggesting that these mutations are an early and persistent feature of bladder cancer." (PMID 40282460, 2025). "Similarly, TERT promoter mutations are nearly ubiquitous across bladder cancer subtypes, facilitating telomerase activation and limitless replicative potential." (PMID 41373802, 2025). "S12), with potential relevance to the CC242-243TT TERT mutations observed in bladder cancers." (PMID 41337590, 2025). "Furthermore, the presence of TERT promoter mutations in the PDD false-positive sites of PDD-TURBT using 5-ALA was considered to be a possible precancerous lesion of bladder cancer." (PMID 40995307, 2025). "Collectively, these results indicate that exposure of the normal urothelium to tobacco carcinogens may increase the risk of bladder cancer through the promotion of clones bearing mutations of the TERT promoter." (PMID 41062697, 2025). "A main characteristic of urinary bladder cancer are mutations in the TERT promoter gene." (PMID 38833173, 2024). "FGFR3 and TERT are the most frequently mutated oncogenes for bladder cancer." (PMID 38994482, 2023). "Note that germline SNPs in both FGFR3 and TERT have been associated with bladder cancer risk." (PMID 38994482, 2023). "In UBC, the telomerase reverse transcriptase (TERT) promoter mutations represent the most recurrent genetic mutations, which have been identified as a significant influence in carcinogenesis development for 60%–80% of bladder cancer patients." (PMID 37081791, 2023). "Finally, the TERT promoter mutation (c.1-124C>T, gain-of-function mutation) has been widely reported in several solid tumors, including bladder cancer, where it plays an important role in tumorigenesis." (PMID 38098507, 2023). "We identified 69 recurrent somatic mutations in 61 core promoters of 62 genes and 28 recurrent germline mutations in 20 core promoters of 21 genes, including TERT, the only gene known with core promoter mutation in bladder cancer, and many oncogenes and tumor suppressors." (PMID 35033028, 2022). "TERT is the only known gene with somatic core promoter mutation in bladder cancer." (PMID 35033028, 2022). "Bladder cancer patients with TERT promoter mutations take a higher risk of recurrence." (PMID 33938397, 2021). "Recently, a study on bladder cancer suggested that TERT promoter mutation has been identified as a potential predictive marker of Bacillus Calmette-Guérin (BCG) treatment which was regarded as one of the first and most successful of all oncological immunotherapies." (PMID 32915164, 2020).
bladder cancer (continued). "Overall, TERT mutations can be found in about 50% of bladder cancers (COSMIC database) and the mutation rate could be as high as 70%." (PMID 31938901, 2020). "The combination of the two plasmids (each targeting either TERT or TERC) led to the strongest bladder cancer growth inhibition, but the underlying mechanism behind this strong combinatory effect was not elucidated in this report and requires further exploration." (PMID 31035374, 2019). "Similarly, in bladder cancer it has been shown that TERT promoter mutations promote a mechanism for high-level telomerase reactivation associated with stable telomere length." (PMID 29463038, 2018). "TERT promoter mutations at early steps during tumorigenesis (e.g., bladder cancer) may therefore generate a ‘stem-like’ cell that can accumulate further mutations without activating senescence checkpoints." (PMID 27483324, 2016). "Additionally, the promoter of telomerase reverse transcriptase (TERT) gene frequently mutated in bladder carcinoma in which ETS1 bond to the altered promoter and promoted bladder carcinoma migration and progression." (PMID 26625313, 2016). "To further investigate whether TERT is associated with clinical severity, we examined its expression in the bladder cancer patients through immunohistochemical staining." (PMID 26143634, 2015). "In addition to somatic TERT promotor mutations, germ line genetic variants have been shown to predispose for breast, ovarian and bladder cancer." (PMID 26143636, 2015). "Importantly, introducing the C228T mutation in NBBCs causes TERT overexpression and transformation of bladder cancer." (PMID 26143634, 2015). "TERT promoter C228T and C250T mutations occur in various malignancies including bladder cancer (BC) and may serve as urinary tumor markers." (PMID 25474136, 2014). "Additionally, bisulfite-treated DNA from bladder cancer-associated fibroblasts, immortalized urothelial cells (TERT-NHUC), and connective tissue originating from a freshly dissected ureter were used for comparison." (PMID 24133654, 2013). "Similarly, TERT promoter mutations, which are highly prevalent in bladder cancer, are often clonal and present in both primary and metastatic lesions, suggesting their role in early tumorigenesis and potential utility as stable biomarkers for monitoring disease progression." (PMID 40191434, 2025). "Thus, TERT promoter mutations may serve as a biomarker for bladder cancer relapse, enabling periodic urine-based monitoring to ensure timely intervention and management." (PMID 39871386, 2025). "We also found a high increase of TERT promoter mutations among older people with a history of smoking, which may explain at least part of the link between smoking and increased bladder cancer risk, given the high frequency of TERT promoter mutations across bladder tumours." (PMID 41062697, 2025). "Therefore, TERT promoter mutations in the bladder mucosa could be the initiation of bladder cancer development." (PMID 40995307, 2025). "TERT promoter mutations may become a potential prediction factor for bladder cancer recurrence." (PMID 33938397, 2021). "Therefore, we hypothesized that TERT promoter mutation was associated with bladder cancer recurrence." (PMID 33938397, 2021). "By contrast, the cost of the NGS-based and ddPCR assays for detecting urinary TERT promoter mutations in bladder cancer developed by our group is about 24€ per sample, and, therefore, has the potential to be easily implemented for cost-effective bladder cancer management strategies." (PMID 32839402, 2020). "TERT promoter mutations were firstly described in sporadic and familial melanoma, and since then they were reported in several cancers, such as central nervous system (43–51%), hepatocellular carcinoma (59%), thyroid (follicular cell-derived tumors) (10%), and notably in bladder cancer (59–80%)." (PMID 31921291, 2019).
bladder cancer (continued). "AssureMDx analyzes DNA from exfoliated urothelial cells in urine to identify mutations (FGFR3, TERT, HRAS) and methylation changes (OTX1, ONECUT2, TWIST1), allowing for highly accurate detection of bladder cancer." (PMID 41228219, 2025). "We monitored proliferation measured as cell index in a bladder cancer cell line with low TERT expression (5637 cells, DepMap TERT TPM = 1.23) after transient transfection with the TERT-FL or TERT-β plasmid." (PMID 39956830, 2025). "This study is the first to demonstrate an association between TERT promoter mutations and PDD false-positive sites, and it further aims to assess the potential of TERT promoter mutations as predictors of bladder cancer recurrence." (PMID 40995307, 2025). "By detecting methylation of specific bladder cancer-related methylation markers such as TERT promoter and ONECUT2 CpG sites, the method achieved a sensitivity of 94.0%, specificity of 93.1%, and an AUC of 0.961 in the validation dataset." (PMID 40191434, 2025). "Mutations in the promoter region of the telomerase reverse transcriptase (TERT) gene are commonly found in many primary tumors, such as bladder cancer and its early-stage lesions." (PMID 40995307, 2025). "Recently, excreted urine from bladder cancer patients was tested for telomerase activity, TERT mRNA, and TERC telomerase RNA with a range of sensitivities and specificities." (PMID 40151802, 2025). "TERT gene promoter, FGFR3 mutations, and HER2 and HER3 mutations were recently identified as driver genetic abnormalities in bladder cancers." (PMID 38255300, 2024). "We monitored cell proliferation after transient overexpression of the TERT-FL and TERT-β isoforms in 5637 cells, a bladder cancer cell line with low TERT expression (DepMap TPM=1.23)." (PMID 39802763, 2024). "Nucleotide changes in TERT promoter were detectable up to 10 years prior to bladder cancer diagnosis." (PMID 38033865, 2023). "Uromonitor, another gene-related biomarker, is capable of detecting minute quantities of TERT promoter and FGFR3 hotspot mutations, common somatic alterations in bladder cancer." (PMID 37762677, 2023). "Genetic mutations in the telomerase reverse transcriptase (TERT) gene and phosphatidylinositol-4,5-bisphosphate 3-kinase catalytic subunit alpha (PIK3CA) gene are prevalent in bladder cancer." (PMID 37945655, 2023). "Large studies are required to better evaluate the frequency of the TERTpm clonal hematopoiesis and its potential role in bladder cancer or its implication in the interpretation of a TERT-positive test." (PMID 36430798, 2022). "•In bladder cancers, FGFR3 SVs were significantly associated with CDKN2A/B and TERT alterations, and a lower TMB." (PMID 36462464, 2022). "TERT is highly expressed in invasive and advanced bladder cancer patients as compared to the early and non-invasive bladder cancer patients." (PMID 34094968, 2021). "In eastern China, the mutation frequencies of GPR126 intron 6, TERT, and PLEKHS1 promoters in UUT-UC patients were significantly lower than those in patients with bladder cancer." (PMID 34660295, 2021). "Polyclonal events were observed in five out of nine whole-organ mapping bladder cancers housing tumor associated normal urothelium, non-invasive urothelial lesions and CIS where different TERT promoter mutations were found compared to MIBC." (PMID 33562516, 2021).
bladder cancer (continued). "The mutation hotspots analyzed in our study should cover more than 90% of bladder-cancer-relevant gain-of-function mutations of the FGFR3 gene and ~80% of TERT promoter mutations, respectively." (PMID 32213857, 2020). "The high sensitivity and specificity of the ddPCR urinary TERT promoter mutations assays in the two independent cohorts investigated in this study provides evidence that these tests could be easily implemented into the clinic for the non-invasive detection of bladder cancer." (PMID 33260905, 2020). "For example, TERT was negatively correlated with chemosensitivity of hepatocellular carcinoma, bladder cancer, and head and neck cancers." (PMID 32373170, 2020). "In 2017, the first report of a human TERT promoter-driven GAL4/upstream activating sequence (UAS) binding system for selective activation of CRISPR/Cas9 targeting the HRAS oncogene in bladder cancer cells was published." (PMID 31035374, 2019). "In support, the plasmid-based delivery of shRNA targeting either TERT or TERC led to durable suppression of bladder cancer cell growth up to 6 days after treatment." (PMID 31035374, 2019). "More recently, a combination of methylation status of TWIST, ONECUT2, and OTX1 with mutational analyses of FGFR3, TERT, and HRAS has been reported to detect bladder cancer with a sensitivity of 97% and a specificity of 83%." (PMID 29907142, 2018). "Two of the most frequently mutated genes in bladder cancer with point-mutation hotspots are FGFR3 and TERT." (PMID 26901314, 2016). "TERT rs2853669 has been shown to modulate both TERT expression and impact on prognosis in bladder cancer and GBM." (PMID 26143636, 2015). "The expression levels of TERT epitope correlated with pathological grades and tumor stages of bladder cancers." (PMID 26143634, 2015). "We examined TERT expression and telomerase activity in all sorted bladder cancer samples by real-time PCR and TRAP (telomeric repeat sequence amplification protocol) assays." (PMID 26143634, 2015). "We analyzed the relationship between expression of TERT and clinicopathological features in bladder cancer patients." (PMID 26143634, 2015). "Suppressing high TERT expression and telomerase activity is considered as a promising goal in bladder cancer therapy." (PMID 26143634, 2015). "We have reported that the presence of the TERT promoter mutation (C228T) in non-malignant bladder urothelium is significantly associated with a higher recurrence rate of bladder cancer." (PMID 40995307, 2025). "Additionally, some studies have reported TERT promoter mutations in early precancerous lesions of various cancers, including HCC, bladder cancer, cutaneous melanoma, and squamous cell carcinoma." (PMID 39871386, 2025). "On this basis, the combination of FGFR3, TERT, and HRAS proto-oncogene mutations resulted in a sensitivity of 93% and a specificity of 89% for the diagnosis of bladder cancer, which shows that the combination of DNA methylation testing has great potential in the detection of bladder cancer." (PMID 39766341, 2024). "The TERT c.-124C>T mutation, observed with a high variant allele frequency (VAF) of 50% even before lurbinectedin treatment in our case, is commonly associated with bladder cancer." (PMID 38920737, 2024). "Therefore, we investigated the usefulness of TERT and PIK3CA mutations as blood biomarkers for bladder cancer." (PMID 37945655, 2023). "There were variable similarities for single genes with endometrial and bladder cancer, but the absence of TERT promoter mutations, the most frequent mutational alterations identified in urothelial carcinomas, argues for a non-urothelial origin." (PMID 34200508, 2021).
bladder cancer (continued). "Two hotspot mutations of the TERT promoter have been detected with high frequency in bladder cancer but not in neighboring normal tissues." (PMID 32839402, 2020). "Two mutations in the promoter of the Telomerase reverse transcriptase gene (TERT), called C228T and C250T, are frequent in various human cancers and particularly in UCs (carcinomas of the bladder and upper urinary tract) where it is seen in 60–85% of cases (74% for non-invasive UCs)." (PMID 33260905, 2020). "On the other hand, ALT is in general absent in bladder cancer, but up to 85% of bladder cancer harbor TERT promoter mutations." (PMID 27438857, 2016). "TERT expression levels are consistent with clinical severity and prognosis of bladder cancer." (PMID 26143634, 2015). "In two population-based case-control studies conducted separately among non-Hispanic whites (NHW) and Asian populations, the TERT rs2736098 polymorphism exhibited a significant association with bladder cancer risk among non-Hispanic whites." (PMID 24260099, 2013). "Furthermore, a previous study in a Greek population revealed a TERT hypermethylation rate of 2.2% in patients with bladder cancer, supporting the observation that variations in DNA methylation exist among different human populations across various macro- and micro-geographical scales." (PMID 38891848, 2024). "The result showed that TERT was not expressed in normal bladder but overexpressed in bladder cancer with core promoter C228T mutation TERT; survival data of CDA, SLC9A1 and SLC24A4 also showed that their expression levels were associated with 5-year survival significantly." (PMID 35033028, 2022). "In addition, within a prospective cohort study, urinary TERT promoter mutations were detected up to 10 years prior to clinical diagnosis of primary bladder cancer and were absent from matched controls." (PMID 33260905, 2020). "Among these three techniques compared in urine from 200 bladder patients, the sensitivity of TERT mRNA, TERC, and telomerase activity for detecting bladder cancer were 96%, 92%, and 75%, respectively." (PMID 40151802, 2025). "NAC has been reported to revert fucoidan-induced apoptosis and downregulations of telomerase reverse transcriptase (TERT), c-myc, Sp1 transcription factor, and AKT expressions in bladder cancer cells." (PMID 35624705, 2022). "Recently, telomerase activity, TERT mRNA, and TERC telomerase RNA were measured in urine of bladder cancer patients with various sensitivities and specificity rates." (PMID 27240403, 2016). "A study from 200 bladder patients comparing these three methods in urine revealed that sensitivity f of TERT mRNA, TERC, and telomerase activity for detecting bladder cancer was 96%, 92%, and 75%, respectively." (PMID 27240403, 2016). "Moreover, TERT expression has been used to detect CTC in blood samples, as well as urothelial carcinoma in the urine of patients with bladder cancer." (PMID 37444476, 2023). "In bladder cancer, GABPA is involved in the recruitment of two transcriptional co-regulators of telomerase expression, namely, TRIM28 (tripartite motif containing 28) and TRIM24, to the mutant TERT promoter −124A." (PMID 38033865, 2023). "The C228T in the core promoter of TERT was detected in 3 bladder cancer cases but absent in all paired blood samples, and no coding mutation in TERT was detected." (PMID 35033028, 2022). "Titration of DNA extracted from the bladder cancer cell lines MGH-U3 (FGFR3 mutant) and SW-780 (TERT promoter mutant) into wtDNA demonstrated that the percentage of mutant reads reliably reflected the percentage of mutant DNA down to levels below the 2.5% threshold used here." (PMID 26901314, 2016).
bladder cancer (continued). "The histologically high grade, deeply invasive and lymphatic-invasive bladder cancers demonstrated significantly higher expression of TERT than the low-grade, superficial, and nonlymphatic-invasive cancers." (PMID 26143634, 2015).